SETD7 (SET domain containing 7, histone lysine methyltransferase)
Diseases named in the same sentence as SETD7 in open-access papers (continued):
Sharing a sentence is not in itself a finding about the gene and the disease.
diabetes (12 papers, 2014 to 2024). "Similar results were also shown in diabetes models in which SETD7 interacts with RelA, facilitating the nuclear translocation of RelA and promoted function of NF-κB to transactivate downstream genes." (PMID 35812730, 2022). "SETD7 is also a potential target for the treatment of several other diseases, such as diabetes, inflammatory diseases and mental disorders." (PMID 30013796, 2018). "Our study may set the stage for epigenetic therapies (i.e. SETD7-targeting approaches) aimed at preventing the activation of pathways (i.e. NFkB) driving trained immunity and pro-atherosclerotic features in diabetes." (PMID 38553774, 2024). "NF-κB regulation by SETD7 might depend on the cellular context, tissue specificity or particular physiological condition, such as in cancer cells or diabetes model." (PMID 35812730, 2022).
gastric cancer (10 papers, 2016 to 2024). A primary or metastatic malignant neoplasm involving the stomach. "In gastric cancer, a reduced expression level of SETD7 was observed in 34.3% (129/376) of patients and was significantly correlated with clinical aggressiveness and a poor prognosis (p < 0.05)." (PMID 38036730, 2023). "Similarly, SETD7 has been found to inhibit cell proliferation and migration in gastric cancer." (PMID 38036730, 2023).
hepatocellular carcinoma (10 papers, 2016 to 2024). A malignant tumor that arises from hepatocytes. "SETD7 is known to stabilize E2F transcription factor 1 (E2F1) in hepatocellular carcinoma, leading to the expression of cyclin E1, cyclin A2, and CDK1, which triggers the cell cycle in tumorigenesis." (PMID 38036730, 2023). "It has been reported that SETD7 plays a critical role in hepatocellular carcinoma, colorectal cancer, lung cancer, and so on." (PMID 35501306, 2022). "In addition, increased SETD7 expression was reported to be involved in metastasis, recurrence and poor prognosis in hepatocellular carcinoma." (PMID 29212211, 2017).
lung carcinoma (9 papers, 2015 to 2026). "We established the model by injecting LLC1 cells s.c. which enabled us to not only study the CPH efficacy in inhibition of lung cancer cells growth but also to assess the role of Setd7 in lung metastasis." (PMID 39522095, 2024). "We performed WB to assess SETD7 protein expression in the different lung cancer cell lines with different metastatic characteristics." (PMID 39522095, 2024). "Future investigations should be done to better understand the mechanism of action of CPH and Setd7 at the molecular level in regulating the different signaling pathways of lung cancer." (PMID 39522095, 2024). "In this paper, we expand and focus on the role of Setd7 and its inhibitor in lung cancer metastasis via rewiring of cellular metabolism." (PMID 39522095, 2024). "The in vivo LLC1 syngeneic lung cancer model found decreased number of metastatic nodules on the surface of lungs of Setd7 KO mice compared to SETD7 WT." (PMID 39522095, 2024). "In lung cancer, SETD7 can inhibit cell proliferation by downregulating cyclins (CCNA1 and CCND1)." (PMID 39522095, 2024). "Hence, we decided to move forward and test CPH efficacy in vivo with syngeneic lung cancer murine model using subcutaneous injection of LLC1 cells in Setd7 WT and KO." (PMID 39522095, 2024). "A recent study shows Setd7 controls the proliferation and genotoxic drug resistance of lung cancer." (PMID 39522095, 2024). "However, with respect to the role of SETD7 in lung cancer, there is a dispute over this matter in the current literatures." (PMID 33372601, 2020). "Setd7 inhibitors, such as CPH, may be a promising candidate for targeting the metabolomic rewiring of lung cancer cells." (PMID 39522095, 2024). "WB results showed overexpression of Setd7 protein in advanced lung cancer cell lines such as A549, H358, and LLC1 compared to the normal lung cell line Beas-2b." (PMID 39522095, 2024). "Yet, the detailed mechanism of action of Setd7 and its inhibitor CPH in lung cancer has not been fully explored." (PMID 39522095, 2024).
osteosarcoma (6 papers, 2015 to 2022). A usually aggressive malignant bone-forming mesenchymal neoplasm, predominantly affecting adolescents and young adults. "Inactivation or elimination of SETD7 causes G1/S cell-cycle arrest in osteosarcoma and pulmonary carcinoma cells after DNA damage." (PMID 35600335, 2022). "In summary, all studies considered the effects of SETD7 in osteosarcoma cell cycle under stress conditions and while some agree that SETD7 prevents cell cycle arrest, others showed the opposite." (PMID 35326563, 2022). "Together, the results suggest that in osteosarcoma cells under DNA damage, SETD7 is needed for cell cycle arrest through methylation of pRb or E2F-1 or PPP1R12A." (PMID 35326563, 2022). "SETD7 increases E2F-1 stability, but inhibits E2F-1-dependent transcription of TP73 in osteosarcoma cells." (PMID 35326563, 2022). "SETD7 methylates E2F-1 at K185 stabilising it to enhance the transcription of pro-apoptotic target genes, BIM1 and TP73, suggesting that SETD7 activity inhibits cell growth and enhances the E2F-1 pro-apoptotic effect in osteosarcoma cells." (PMID 35326563, 2022).
breast tumor (5 papers, 2016 to 2022). "This analysis clearly showed that SETD7 mRNA is significantly lower in breast tumours compared with the adjacent normal tissue." (PMID 36551516, 2022). "To compare the expression of SETD7 in breast tumours and adjacent normal tissue, we used the publicly available online tool TNMplot comprising RNA-seq data of paired tissue samples from 112 patients." (PMID 36551516, 2022).
cervical carcinoma (5 papers, 2016 to 2022). A carcinoma arising from either the exocervical squamous epithelium or the endocervical glandular epithelium. "HeLa cells were used to study the SETD7 role in cervical cancer cell line." (PMID 35326563, 2022). "In colorectal and cervical cancers, the evidence indicates that SETD7 is a negative regulator of proliferation." (PMID 35326563, 2022).
glioma (5 papers, 2022 to 2023). A benign or malignant brain and spinal cord tumor that arises from glial cells (astrocytes, oligodendrocytes, ependymal cells). "To determine the functional role of SETD7 in the development of the glioma, we used the SETD7 siRNA to perform the knockdown experiment." (PMID 35501306, 2022). "In this study, we found that SETD7 knockdown inhibited the proliferation of glioma via AKT pathway." (PMID 35501306, 2022). "For example, researchers discovered that SETD7-mediated H3K4me3 enrichment on the lncRNA DRAIC promoter regulated the growth and metastasis of gliomas." (PMID 35600335, 2022). "The results showed that knockdown of SETD7 inhibited the proliferation and the AKT pathway of glioma." (PMID 35501306, 2022).
liver cancer (4 papers, 2016 to 2022). An epithelial or non-epithelial malignant neoplasm that arises from the liver. "SMMC-7721, QGY-7703, Bel-7404, HCC-0010, HepG2, and HL-7702 cells were detected by Western blot analysis to determine the SETD7 expression in different liver cancer cell lines and the normal liver cell line." (PMID 27183310, 2016).
lung adenocarcinoma (4 papers, 2020 to 2026). A carcinoma that arises from the lung and is characterized by the presence of malignant glandular epithelial cells. "This study aims to elucidate the role of SETD7 in the regulation of the STING-dependent immune response in human lung adenocarcinoma (LUAD) cells." (PMID 42123601, 2026).
non-small cell lung carcinoma (4 papers, 2016 to 2024). A group of at least three distinct histological types of lung cancer, including non-small cell squamous cell carcinoma, adenocarcinoma, and large cell carcinoma. "In non-small cell lung cancer (NSCLC), SETD7 can specifically methylate the Gli3 at K436 and K595 sites, increasing the stability and DNA binding ability of Gli3, thereby enhancing the activation of Shh signaling." (PMID 38904013, 2024).
Obesity (4 papers, 2018 to 2024). Accumulation of substantial excess body fat. "In summary, we have provided evidence for a direct transcriptional regulation of SetD7 by PPARγ, and this molecular interaction is manifested during a transient phase of adaptive β-cell response following Px as well as during metabolic stress of HFD-induced obesity and insulin resistance." (PMID 34592314, 2021).
ovarian carcinoma (4 papers, 2016 to 2024). A malignant neoplasm originating from the surface ovarian epithelium. "Furthermore, SETD7 exerts a tumor-promotive function in ovarian cancer (OC) cells in a K51 methylation-dependent manner." (PMID 39725038, 2024). "Moreover, SETD7 plays a tumor-promotive function in ovarian cancer (OC) cells in a K51 methylation-dependent manner." (PMID 39725038, 2024).
alopecia areata (3 papers, 2017 to 2024). Loss of scalp and body hair involving microscopically inflammatory patchy areas. "It shows that alopecia areata increased KDM5A, MLL, SETD7, and G9A expression, as well as reduced LSD1, KDM4A, and KDM4B expression." (PMID 39046182, 2024).
clear cell renal cell carcinoma (3 papers, 2024 to 2025). "However, the biological function and underlying molecular mechanism of SETD7 in clear cell renal cell carcinoma (ccRCC) remain unclear." (PMID 38904013, 2024). "In clear cell renal cell carcinoma, SETD7 catalyzes the methylation of lysine 5 and 300 on the TAF7 protein, leading to TAF7 deubiquitination and stabilization." (PMID 41203594, 2025). "SET domain containing 7 (SETD7), a member of histone methyltransferases for H3K4me1, is abnormally expressed in multiple tumor types, including clear cell renal cell carcinoma (ccRCC)." (PMID 39602041, 2025).
colon cancer (3 papers, 2018 to 2024). "Additionally, SETD7/9 was shown to suppress histone deacetylase-6 (HDAC6)-mediated activation of the ERK signaling cascade, showing that SETD7/9 has an anti-tumor role in colon cancer." (PMID 38827317, 2024).
pulmonary fibrosis (3 papers, 2018 to 2022). Chronic progressive interstitial lung disorder characterized by the replacement of the lung tissue by connective tissue, leading to progressive dyspnea, respiratory failure, or right heart failure. "Epigenetic modification on K70 of SMAD7 by SETD7-mediated methylation decreases the protein stability of SMAD7 by ubiquitination-dependent manner via Arkadia E3 ligase in mouse models of pulmonary fibrosis." (PMID 35812730, 2022). "As such, SETD7 might be a potential therapeutic target for lung fibrosis or cancers." (PMID 35812730, 2022).
diabetic retinopathy (2 papers, 2022 to 2025). "In diabetic retinopathy research, SETD7 promotes KEAP1 expression by enhancing H3K4me1 at the KEAP1 promoter region, accelerating retinal endothelial cell damage." (PMID 41203594, 2025).
Glucose intolerance (2 papers, 2021 to 2024). Glucose intolerance (GI) can be defined as dysglycemia that comprises both prediabetes and diabetes. "SetD7 mRNA levels were downregulated within a week of HFD that coincided with development of early glucose intolerance in the HFD mice." (PMID 34592314, 2021). "The HFD mice develop glucose intolerance within a week that coincided with reduction in expression of SetD7 along with previously reported decreased expression of MafA, Glut2, Gck, GIPR, and PPARγ in islets." (PMID 34592314, 2021). "A mouse model with MIP1-CreERT-driven β-cell-specific knockout of SetD7 developed glucose intolerance with islet specific downregulation of the critical β-cell genes Pdx1, MafA, Glut2, and Gck." (PMID 34592314, 2021). "Further in vivo evidence for molecular interaction of PPARγ and SetD7 was obtained using a pancreas-specific (PANC) PPARγ−/− knockout mouse that we previously characterized and observed to display glucose intolerance, but no change in β-cell mass." (PMID 34592314, 2021).
nephropathies (2 papers, 2016 to 2017). "Three genes (Frem2, Foxo1 and Setd7) have been implicated in nephropathy." (PMID 27736906, 2016). "Of these, Frem1, Foxo1, and Setd7 have been implicated in the pathogenesis of nephropathy." (PMID 27736906, 2016).
Cachexia (1 paper, 2020). Severe weight loss, wasting of muscle, loss of appetite, and general debility related to a chronic disease. "In cachexia, SENP3 regulation of SETD7 is impaired, causing altered MyHC-II expression and disorganized sarcomeres." (PMID 33192553, 2020).
esophageal squamous cell carcinoma (1 paper, 2025). Esophageal squamous cell carcinoma (ESCC) is a type of esophageal carcinoma (EC) that can affect any part of the esophagus, but is usually located in the upper or middle third. "However, the biological functions and epigenetic regulatory mechanisms of SETD7 in esophageal squamous cell carcinoma (ESCC) remain unclear." (PMID 41203594, 2025).
helminth infections (1 paper, 2016). "Thus, loss of SETD7 in IECs leads to increased resistance to chronic helminth infection independent of the immune response, identifying a potential new therapeutic target to treat persistent helminth infections." (PMID 27598373, 2016). "To test if SETD7 played a role in the development of chronic helminth infection, we infected mice with a low-dose (~30 eggs) of T. muris infection." (PMID 27598373, 2016). "In this study we identify a critical role for IEC-intrinsic expression of Setd7 in immunity to helminth infection." (PMID 27598373, 2016). "In this study we describe the role of SETD7 during helminth infection." (PMID 27598373, 2016).
intestinal infection (1 paper, 2018). "Mice with targeted disruption of SET domain-containing protein 7 (Setd7) showed increased resistance to intestinal infection of helminthic origin by Trichuris muris." (PMID 29597279, 2018).
medulloblastoma (1 paper, 2025). A malignant, invasive embryonal neoplasm arising from the cerebellum.
myocardial ischemia (1 paper, 2025). A disorder of cardiac function caused by insufficient blood flow to the muscle tissue of the heart. "Furthermore, another recent research has demonstrated that SETD7 can methylate Yes-associated protein (YAP) during myocardial ischemia, promoting its retention in the cytosol and diminishing the transcription of antioxidant genes such as manganese superoxide dismutase (MnSOD) and catalase (CAT)." (PMID 41371168, 2025).
neuroblastoma (1 paper, 2021). Neuroblastoma (NB) is the most common solid, extracranial childhood tumor. "Indeed, the treatment of SH-SY5Y neuroblastoma cells stably expressing GFP-0N4R Tau with the selective SETD7 inhibitor (R)-PFI-2 significantly reduced both meK132- and meK130-modified Tau." (PMID 34215303, 2021).
parasitic infections (1 paper, 2016). "We therefore sought to study the role of SETD7 during parasitic infections." (PMID 27598373, 2016).
small intestine carcinoma (1 paper, 2022). "However, in PCa, BC and small intestine carcinoma, SETD7 expression and activity is needed for proliferation." (PMID 35326563, 2022).
small intestine tumours (1 paper, 2022). "Consistently, in organoids derived from small intestine tumours in ApcMin/+ mice treated with the SETD7 inhibitor (R)-PFI-2 showed reduced initiation of spheres and lower Wnt-dependent gene expression (Lgr5, Axin2 and Lyz1)." (PMID 35326563, 2022).
cancer (53 papers, 2015 to 2026). A tumor composed of atypical neoplastic, often pleomorphic cells that invade other tissues. "Accumulating evidence suggests that the expression of Setd7 is associated with cancer development and progression." (PMID 39522095, 2024). "Other studies have also analysed SETD7 mRNA in public databases and found downregulation of SETD7 transcript in GC (TCGA: 415 cancer and 35 normal) associated with shorter OS." (PMID 35326563, 2022). "High SETD7 protein correlated with higher stromal scores in CPTAC dataset and high SETD7 mRNA with cancer-associated fibroblasts (CAFs), endothelial cells, and neutrophil signatures in the TCGA-BRCA dataset." (PMID 36551516, 2022). "In a recent systematic review, we were able to associate high SETD7 activity with inhibition of epithelial–mesenchymal transition in all the cancer types where this process had been studied, including BC." (PMID 36551516, 2022). "As such, SETD7 has been implicated in both the basic functions of normal tissues but also in several pathologies, such as cancers." (PMID 35812730, 2022). "The study may provide useful information to help understand the underlying mechanism of methylation related to SETD7 during the development of ccRCC cancer and provide novel effective targets for cancer therapy." (PMID 38904013, 2024). "It has been reported that SETD7/9 has also been associated with chemoresistance in certain cancers." (PMID 38827317, 2024). "Setd7 expression is associated with increased proliferation and poor prognosis of various cancers." (PMID 39522095, 2024). "According to publicly available RNA-seq data and microarray analyses, SETD7 lysine methyltransferase participates in interferon signaling in cancer cells." (PMID 42123601, 2026). "Pan-cancer analysis revealed that SETD7 expression was significantly upregulated in ESCC tissues compared to normal tissues." (PMID 41203594, 2025). "As a member of the HKMT family, SETD7 plays critical roles in tumorigenesis across multiple cancer types." (PMID 41203594, 2025). "Future studies require a comprehensive investigation to elucidate how SETD7 orchestrates ferroptosis regulation in cancers." (PMID 41203594, 2025). "Setd7 regulates cancer cell proliferation by influencing β-catenin stability in both in vitro and in vivo models." (PMID 39522095, 2024). "The controversial roles of SETD7 in various cancer types imply that the effects of SETD7 on cancer development depend on its interacting proteins and the particular cellular context." (PMID 39725038, 2024). "SETD7 regulates a variety of cancer-related processes, in a tissue-type and signalling context-dependent manner." (PMID 38670954, 2024). "CPH has been recognized as a potent Setd7 inhibitor with anti-tumor activity in several cancer models." (PMID 39522095, 2024). "Of note, more attention should be paid to the epigenetic modifications of the ZBTB20 gene in cancer cells since the gene expression of ZBTB20 is differentially downregulated in HCC cells after knockdown of histone lysine methyltransferase SETD7." (PMID 38397429, 2024). "Conversely, the role of the PKMT, SETD7/9 is contradictory in cancer, with some studies showing it has a tumor suppressive role and others showing its importance in cancer-related processes and drug resistance." (PMID 38827317, 2024). "In this study, we showed that SETD7 was significantly highly expressed in ccRCC tissues and cell lines, which is highly consistent with the bioinformatics analysis results in pan-cancer." (PMID 38904013, 2024). "Nonetheless, SETD7 regulates cancer-related processes in a tissue type- and context-dependent manner." (PMID 39522095, 2024). "Knockdown of SETD7 inhibited cancer cell proliferation, induced G1/S cell cycle arrest, and increased apoptosis." (PMID 37602329, 2023). "As a result, SETD7 facilitates glycolytic adaptation and the survival of cancer cells under hypoxic conditions." (PMID 38036730, 2023).